CRP (C-reactive protein)
Diseases named in the same sentence as CRP in open-access papers (continued):
Sharing a sentence is not in itself a finding about the gene and the disease.
anemia (continued). "Laboratory abnormalities include anaemia, thrombocytopenia, hyponatremia, hypoalbuminaemia, and elevations of C-reactive protein (CRP), KSHV viral load, interleukin-6 (IL-6), and interleukin-10 (IL-10)." (PMID 26242311, 2015). "Episodes of BSI in the high CRP group had a significantly higher rate of abnormal laboratory findings, including leucopenia, anemia, thrombocytopenia, and metabolic acidosis compared to those in the low CRP group." (PMID 26259626, 2015). "This study has limitations with reference to the measurement of other marker of inflammation like serum CRP and details data about treatment of anemia particularly ESA disages." (PMID 26644884, 2015). "Her blood laboratory data revealed inflammation, with a C-reactive protein (CRP) level of 12.84 mg/dL and white blood cell count of 16,100/μL (neutrophils, 89.9%), and anemia, with a hemoglobin concentration of 5.8 g/dL and hematocrit of 19.6%." (PMID 26110104, 2015). "Among the laboratory findings, anemia, lymphocytopenia, total protein, albumin,and C-reactive protein were significant." (PMID 26070207, 2015). "A higher rate of anemia and coagulopathy was also noted, and the CRP level tended to vary widely between cases with benign courses and those with a fulminant course." (PMID 25875677, 2015). "The incidence of anemia among 4 major cancers (gastric, colorectal, lung cancer and hepatocellular carcinoma), and biochemical features of anemia using ferritin, CRP, hepcidin and soluble transferrin receptor (sTfR) were assessed." (PMID 26517509, 2015). "Those diagnosed with active TB within 96 weeks of ART initiation were five times as likely to have low albumin and two to three times as likely to have highest-quartile levels of CRP and IP-10, detectable plasma LPS, and anemia." (PMID 25719208, 2015). "The relationship between anemia and inflammatory process in hemodialysis patients as assessed by high serum CRP has been addressed in several studies but the data regarding serum albumin and anemia in hemodialysis patients are scarce." (PMID 26644884, 2015). "Anemia workup included complete blood count, ferritin, transferrin saturation, serum levels of folic acid and vitamin B12, and C-reactive protein (CRP) concentration." (PMID 25705682, 2015). "Various laboratory abnormalities have also been found, including anemia, thrombocytosis, thrombocytopenia, hypoalbuminemia, hypergammaglobulinemia, and increased C-reactive protein and erythrocyte sedimentation rate." (PMID 25884809, 2015). "Laboratory examination showed a normocytic anemia Hb 7.0 g/dL, normal leukocyte count, an elevated C-reactive protein (CRP 246 mg/liter), and erythrocyte sedimentation rate (ESR 99 mm/h)." (PMID 26266064, 2015). "Compared to patients without MACE, these patients were older, more likely to have CLI, polyvascular disease, anemia, elevated CRP, and impaired renal function." (PMID 26321028, 2015). "Laboratory tests revealed a decreased white blood cell count (WBC, 4,100/mm3) with anemia (Hb 7.6 g/dL), and increased C-reactive protein levels (1.18 mg/dL)." (PMID 25346193, 2014). "Prevalence of moderate and severe anemia, serum CRP levels, and eGFR levels were comparable among all frailty categories for both the CHS and SOF indexes." (PMID 24393272, 2014). "Tumor stage, pathological grade, histological vein invasion, tumor necrosis, UISS, female gender, anemia, CRP, serum VEGF level and VEGF IHC-expression were significant univariate factors in predicting postoperative recurrence." (PMID 24938498, 2014). "Piperacillin/tazobactam was initiated but after 2 days he developed hypoxemia, vascular shock, severe anemia, lymphopenia, and high C-reactive protein." (PMID 25412755, 2014). "Laboratory investigations demonstrated mild anaemia (Hb: 9 g/dL), raised CRP at 118 mg/l and leucocytosis (WCC 27 × 103/μl).A pelvic US showed bilateral complex, predominantly cystic pelvic masses, inseparable from each other." (PMID 27231558, 2014).
anemia (continued). "Laboratory tests revealed a decreased white blood cell count with anemia and increased C-reactive protein levels." (PMID 25346193, 2014). "Laboratory findings also show decreased coping capability of infected and indomethacin treated rats: higher white blood cell counts, increased neutrophil ratio, anaemia, decreased concentration of serum proteins (albumin, globulin, total protein) and CRP." (PMID 25001579, 2014). "A blood test showed anemia (a hemoglobin level of 6.1 g/dl), a low albumin level (2.4 g/dl), a high CRP level (13.59 mg/dl), a low platelets count (8.7×104/μl) and hyper gammaglobulinemia (2,993 mg/dl)." (PMID 24438824, 2014). "Blood tests revealed anemia (hemoglobin: 8.3 g/dl), thrombocytopenia (3.3×104/μ), a low albumin level (2.3 g/dl) and a high CRP level (10.75 mg/dl)." (PMID 24438824, 2014). "Very high LAM ODs were seen in those with severe anaemia and in those with greatly elevated CRP levels." (PMID 25075867, 2014). "After 2 days, he developed hypoxemia, vascular shock, severe anemia, lymphopenia (300/mm3), and high C-reactive protein (137.5mg/L; normal range, NR, <5)." (PMID 25412755, 2014). "Elevated ESR and CRP levels, impaired liver function tests, and anemia are frequently observed laboratory findings in GCA and were also evident in our case." (PMID 24523978, 2014). "Further to anemia management, the administration of iron also appeared to result in decreases respectively normalization of white cell count, platelets and C-reactive protein." (PMID 25326048, 2014). "LAM OD was also substantially higher among patients with severe anaemia, the highest plasma CRP concentrations (≥200 mg/L) and in those with neutrophilia (>7.5×109/L)." (PMID 25075867, 2014). "Focussing on biochemical abnormalities, anaemia, leukophilia, raised CRP, hyponatraemia, raised creatinine, and hyperglycaemia, the LRINEC can aid differentiation of necrotising soft tissue infections from other soft tissue infections." (PMID 25506031, 2014). "ESR is affected by a multitude of compounding factors, such as age, anemia and hypoalbuminemia; whereas CRP is affected only by the presence or degree of inflammation." (PMID 23819854, 2013). "Laboratory studies suggest chronic infection with findings including anemia, hypoproteinemia, elevation of erythrocyte sedimentation rate and C-reactive protein." (PMID 22565800, 2013). "Anaemia was common, as well as biological inflammatory syndrome (raised CRP, hyper-fibrinaemia and accelerated sedimentation rate) and leucocytosis." (PMID 24217164, 2013). "In the sickest patients with the lowest CD4 cell counts, highest CRP concentrations or severe anemia, the sensitivity of a single Xpert MTB/RIF test was more than twice that of smear microscopy." (PMID 24168211, 2013). "Upregulation of proinflammatory cytokines leads to elevated levels of C- reactive protein (CRP) and albumin and chronic inflammation is also related to the development of anemia frequently referred as anemia of the chronic disease." (PMID 23294910, 2013). "The aim of this study was to investigate the association between serum C-reactive protein (CRP) as the marker of inflammation with serum ferritin level and its role in the severity of anemia of hemodialysis (HD) patients." (PMID 25340139, 2013). "Among female patients with hypergammaglobulinemia, the presence of anemia, leukopenia, and normal CRP values together was 95% predictive for the presence of autoimmune disease." (PMID 24180594, 2013). "Initial lab results revealed moderate increase of CRP, anemia, thrombocytopenia, and increased liver enzymes." (PMID 23951370, 2013). "Anaemia, nutrition (albumin, prealbumin), and inflammatory markers (CRP, thrombocytosis, and erythrocyte sedimentation rate) cannot be recommended for diagnostics of NSAID-induced enteropathy." (PMID 24382953, 2013).
anemia (continued). "Initial lab results revealed a moderate increase of CRP, anemia, thrombocytopenia, prolonged activated partial thromboplastin time (aPTT) and prothrombin time (PT), increased liver enzymes, and decreased albumin and hematocrit (Ht)." (PMID 23951370, 2013). "Iron deficiency anemia (11g/dL) and signs of inflammation: erythrocyte sedimentation rate (ESR) of 37mm and C - reactive protein (CRP) of 74mg/L were noted." (PMID 24396560, 2013). "Except for a stable anemia and an increased CRP (54 mg/l, normal range <5 mg/l), laboratory values were within normal range with normal TSH and negative thyroid autoantibodies." (PMID 23341990, 2013). "Anemia, altered bone mineral metabolism, and inflammation (expressed by C-reactive protein) were also observed." (PMID 22860108, 2012). "The major clinical manifestations were thrombocytopenia, anaemia and elevated values of C-reactive protein." (PMID 22401583, 2012). "Only in trochanateric HF was anaemia on admission predictive for a marked inflammatory response and lower leptinaemia had a "protective effect" (suppressed CRP)." (PMID 22333003, 2012). "Serum ferritin concentrations were, consistent with serum CRP concentrations and the clinical features, higher in the severe anemia group." (PMID 23272266, 2012). "Laboratory tests revealed mild anemia (Hb 9.7 g/dL) and elevation of serum C-reactive protein (CRP)." (PMID 23203078, 2012). "Thrombocytopenia, anaemia and elevated values of C-reactive protein were the laboratory test abnormalities observed in this case." (PMID 22401583, 2012). "More specifically, persisting abnormalities included high ferritin levels (n = 4), anemia (n = 4), leucocytosis (n = 3), thrombocytosis (n = 2), high CRP levels (n = 2), elevated ESR (n = 3), and elevated liver enzymes (n = 2)." (PMID 21682863, 2011). "In conclusion, our study demonstrates that patients requiring high-dose ESA for treatment of CKD-related anemia are more likely to have increased levels of the pro-inflammatory biomarkers IL-6 and CRP." (PMID 22152013, 2011). "A majority of patients presented with anemia (58%), low serum albumin (70%), elevated CRP (> 10 mg/L; 59%)." (PMID 21406082, 2011). "A laboratory analysis revealed anemia (Hemoglobin; 9.7 g/dl) and elevated C-reactive protein (3.01 mg/dl)." (PMID 21902830, 2011). "Laboratory tests showed anemia and inflammatory reactivity, hemoglobin (Hgb) was 9.7 g/dl and C-reactive protein (CRP) was 3.01 mg/dl." (PMID 21902830, 2011). "Majority of the patients presented anemia (65%), low albumin level (77.5%) and high CRP level (54%)." (PMID 20537187, 2010). "Abnormal laboratory findings include anemia, hypoalbuminemia, hypergammaglobulinemia, and increased acute-phase proteins such as CRP." (PMID 20981316, 2010). "The iron values at the lower end of the reference range, normal ferritin, normal or slightly low TIBC, and high CRP concentration support the diagnosis of anemia of chronic disease (ACD)." (PMID 20798868, 2010). "Neutropenia and splenomegaly with elevated erythrocyte sedimentation rate, elevated C-reactive protein and anemia of chronic disease pointed toward connective tissue disorder." (PMID 19946450, 2009). "Other laboratory findings include anemia, an elevation of the white blood cell count, and increases in the C-reactive protein (CRP) level and erythrocyte sedimentation rate (ESR)." (PMID 20062763, 2009). "Although levels of CRP, a marker of an acute phase response, were mostly increased in all children, the finding of significantly raised levels among children with functional iron deficiency supports the hypothesis that these children have anaemia of inflammation." (PMID 19638538, 2009). "A month later, he was readmitted to our hospital because of dyspnea, fever, mild anemia with elevated CRP on laboratory tests and a right-sided pleural effusion on chest X-ray." (PMID 19203367, 2009).
anemia (continued). "As the correlation between CRP and ZTT was weak (R = 0.12, P = 0.02), if chronic inflammation is indeed a cause of increased frequency of anemia among institutionalized persons, further studies assessing this possibility are required." (PMID 16584554, 2006). "The inverse correlation of hemoglobin with AGP, CRP, and IL-6 suggests the role of proinflammatory cytokines and inflammation in the anemia of chronic infection." (PMID 15588289, 2004). "In the ESR model, C-reactive protein (CRP) positivity was the strongest independent predictor (adjusted odds ratio [aOR] 7.81, p<0.001), whereas anemia was not independently associated after adjustment (aOR 1.45, p=0.305)." (PMID 41798660, 2026). "Blood tests found: anaemia, elevated C-reactive protein and hyperlymphocytosis." (PMID 41564509, 2026). "SHAP analysis highlighted tumor size, operative duration, preoperative anemia, postoperative neutrophil-to-lymphocyte ratio (NLR), intraoperative blood loss, C-reactive protein (CRP), intraoperative hypoxemia, and perioperative blood transfusion as the dominant predictors of AKI." (PMID 41971434, 2026). "In the context of her symptoms, anemia raised our clinical suspicion of an underlying autoimmune condition, and we ordered haptoglobin, lactate dehydrogenase, estimated sedimentation rate (ESR), C-reactive protein (CRP), HIV, and hepatitis studies." (PMID 40443590, 2025). "70.2% of patients had WBC > 10,000/mm3, 73.0% had CRP > 10 mg/L and 37.9% had anaemia." (PMID 40552167, 2025). "The laboratory and biomarkers variables more frequently identified among patients with PTB were prediabetes (46%), anaemia (59%), high neutrophils count (37%), low lymphocytes count (27%), high ferritin level (39%), CRP > 10 mg/L (79%), high alkaline phosphatase (43%), and low albumin level (58%)." (PMID 40028635, 2025). "A nomogram incorporating all significant predictors from the final logistic regression (malnutrition, BMI <18.5, anemia, elevated CRP, advanced FIGO stage, ovarian cancer, open surgery, preoperative lymphopenia, and age ≥60) was developed to allow individualized risk estimation." (PMID 41169363, 2025). "ESR may be useful in conjunction with CRP and FC for a broader view of inflammatory status, particularly in cases where CRP response is minimal, though it can be influenced by factors like anemia and pregnancy." (PMID 39861141, 2025). "Increased C-reactive protein levels, lower renal function, anemia, and impaired ADL observed in patients with lower GNRI categories might be a result of this vicious cycle." (PMID 40894836, 2025). "Patients often present with anemia and elevated inflammatory markers, such as ESR and CRP, consistent with anemia of chronic disease rather than anemia caused by nutritional deficiencies, consumption, or malignancy." (PMID 41153501, 2025). "Laboratory findings included mild normocytic normochromic non‐regenerative anaemia, mild neutrophilia, marked hyperglobulinaemia, decreased A/G ratio, increased serum CRP concentration, increased ALT activity, marked hyperbilirubinaemia and moderate hypokalaemia." (PMID 39814065, 2025). "According to Polizzotto criteria, KICS was diagnosed due to the presence of the following signs/symptoms: fever, fatigue, respiratory symptoms, anemia, thrombocytopenia, hyponatremia, splenomegaly, and body cavity effusions plus the presence of elevation of CRP and HHV‐8 elevated viremia." (PMID 39731652, 2025). "The current illness was noticed by clinicians one month before hospitalization, during routine post-transplant investigations, when the patient was found to have bicytopenia (mild anemia with thrombocytopenia) accompanied by an elevated C-reactive protein (CRP)." (PMID 40005769, 2025).
anemia (continued). "At presentation, laboratory tests were remarkable for anemia (Hgb = 7.7 g/dL) marked elevation in acute-phase reactants (CRP = 425 mg/L; procalcitonin = 0.33 ng/mL), and white blood cells with neutrophilic predominance (leukocytes: 14,100 cells/mm3; neutrophils: 85.4%)." (PMID 40005556, 2025). "Our findings are consistent with prior studies showing that CRP levels may remain uniformly elevated in institutionalized older adults, making it difficult to use CRP alone as a distinguishing factor for anemia etiology." (PMID 40836330, 2025). "Therefore, laboratory findings in GCSS typically demonstrate neutrophilic leukocytosis along with elevated inflammatory markers, including erythrocyte sedimentation rate and C-reactive protein, and potentially mild anemia and thrombocytosis." (PMID 41211350, 2025). "The addition of hemoglobin and hematocrit slightly improved the explanatory power, suggesting that anemia and hematological status may play a minor role in influencing CRP levels." (PMID 40332145, 2025). "In addition, laboratory abnormalities consistent with a CanL active form (i.e., mild normocytic normochromic anemia and increased CRP) were also present." (PMID 40711313, 2025). "She presented with elevated inflammatory markers (CRP 81.1 mg/L, procalcitonin 0.13 ng/mL), hypoalbuminemia (30.12 g/L), anemia (hemoglobin 6.3 mmol/L), and neutrophil-to-lymphocyte ratio rising from 2 to 26—all findings suggestive of fulminant systemic inflammation." (PMID 41262899, 2025). "Blood reports were normal except for mild anaemia and an elevated C-reactive protein (CRP)." (PMID 40881814, 2025). "The results revealed mild anemia, elevated inflammatory markers such as C-reactive protein (CRP) and erythrocyte sedimentation rate (ESR), which are typically high in HSP due to systemic vasculitis and cytokine-mediated endothelial injury, which stimulate the acute-phase response." (PMID 40951155, 2025). "Blood tests revealed stage 3 acute kidney injury, deranged liver function tests, anaemia with a haemoglobin of 103 g/L, thrombocytopenia (platelets 136 × 109/L), and a significantly elevated C-reactive protein (CRP) of 342 mg/L, indicating significant inflammation and multiorgan dysfunction." (PMID 41040750, 2025). "Additional laboratory findings may include elevated C-reactive protein, anemia, thrombocytopenia, hypoalbuminemia, and hyponatremia." (PMID 39912008, 2025). "Based on the results of multivariate stepwise logistic regression analysis, a predictive model for anemia in AS was established as Logit(P) = −5.02 + 2.041 × gender −1.11 × BMI(body mass index) category + 1.103 × ossification category + 0.942 × CRP category + 1.476 × ESR category." (PMID 39908327, 2025). "Interestingly, in terms of laboratory indicators, the inflammatory markers like WBC, neutrophil ratio, PCT, CRP, and positivity rates for serum G and GM tests were higher in the anemia group compared to the normal group (p < 0.05)." (PMID 41179861, 2025). "Laboratory findings of anemia leukocytosis, and elevated CRP levels have been reported." (PMID 40731941, 2025). "Participants with anemia also showed higher levels of Hs-CRP." (PMID 41383345, 2025). "To enable individualized preoperative infection risk estimation, we deployed the five variables used in the preoperative model to a multivariable logistic regression model incorporating age (log-transformed), anemia, CRP (log-transformed), ASA score, and surgical delay (log-transformed)." (PMID 41302186, 2025). "In addition, 33.3% carried the sickle cell trait, and 35.0% had elevated C-reactive protein, suggesting anemia of inflammation." (PMID 40723025, 2025). "Other lab anomalies may include anemia, thrombocytopenia, elevated C-reactive protein (CRP) and erythrocyte sedimentation rate (ESR), impaired liver function, and atypical lymphocytes on peripheral blood smear." (PMID 40842759, 2025).